APOE (apolipoprotein E)
Diseases named in the same sentence as APOE in open-access papers (continued):
Sharing a sentence is not in itself a finding about the gene and the disease.
Cognitive impairment (continued). "Within the limitation of no APOE genotyping data, this cross-sectional study suggests a significant relationship of tooth loss to MMI and cognitive impairment." (PMID 21194415, 2010). "Especially in severe TBI patients, the strong negative correlation between ApoE and cognitive impairment indicates that early elevation of ApoE may predict poor neurological outcomes, serving as a reference for early rehabilitation and clinical management." (PMID 41394006, 2025). "According to some interpretations, the lack of ApoE interventions and/or their success to date, as well as the fact that Aβ is observed in aged individuals with no cognitive impairment, has cast some doubt on the Aβ hypothesis with some investigators." (PMID 40149482, 2025). "Additionally, key covariates potentially influencing cognitive impairment prevalence, such as body mass index, age, comorbidities, education, and apolipoprotein E, were not assessed due to insufficient data." (PMID 41114787, 2025). "However, the degree of cognitive impairment was found to be associated with the number of Aβ plaques in subjects with FAD but not in those with SAD, irrespective of the APOE allele." (PMID 40722873, 2025). "However, the relationship between ApoE ε4 and GSK‐3β in the cognitive impairment of T2DM patients remains unclear." (PMID 37700547, 2023). "We first estimated the age-related trajectory of cognitive impairment, measured through MMSE total score, using the Hamiltonian Markov chain Monte Carlo method in PSEN1 E280A mutation carriers and non-carriers, irrespective of APOE genotype." (PMID 37612284, 2023). "In addition, a case-control study in 24 participants with mild cognitive impairment compared to 24 age-matched controls found that APOE genotype was not correlated with response to PAS." (PMID 37391420, 2023). "One potential explanation is that features like neuroimaging data, APOE genotype, or biomarkers exhibit higher discriminatory power in detecting AD pathology, whereas cognitive impairment alone may not be sufficient to differentiate pathological burden." (PMID 37939874, 2023). "However, the mechanism by which ApoE affects lipid metabolism and cognitive impairment through the gut microbiota brain axis has not been investigated to date." (PMID 36188475, 2022). "APOE ε4 carriers also display breakdown of the blood–brain barrier in the hippocampus and parahippocampal cortex before the onset of cognitive impairment and independent of Aβ and tau pathology." (PMID 34581957, 2022). "Although little evidence supports the interaction of APOE and altitude, considering that hypoxia-induced cognitive impairment is regulated by the APOE genotype, APOE ε4 may be less frequent in highland populations." (PMID 35149974, 2022). "As a result, animals lacking the ApoE gene displayed cognitive impairment." (PMID 35810473, 2022). "A study on the participants with the ApoE genotype suggested a decreased cognitive deficit in ApoE4 noncarriers, who might have had comparatively less advanced AD." (PMID 33925063, 2021). "Our results suggested that the odds of cognitive impairment was 17% (95% CI: 1% to 30%) lower among those APOE ε4 noncarriers (versus carriers) and 52% lower among those with healthy (versus unhealthy) lifestyle after controlling for sociodemographic, disability, and a number of chronic diseases." (PMID 34061824, 2021). "However, a considerable fraction of older adults display abnormal accumulation of amyloid in the absence of overt cognitive impairment, with the frequency of this finding modified by age, APOE (apolipoprotein E) ɛ4 status, and sex, among other factors." (PMID 33757599, 2021). "However, no studies have investigated the effect of APOE-ε4 and group differences in modulating the cholinergic basal forebrain–amygdala network for subjects with different levels of cognitive impairment." (PMID 34721251, 2021).
Cognitive impairment (continued). "Together, these previous findings may help to explain the cognitive impairments exhibited by mice lacking ApoE or expressing ApoE4 particularly in spatial learning/memory and in olfactory memory, two neurogenic-dependent behaviors." (PMID 32119690, 2020). "In summary, by measuring serum lipids and cognitive function, this cross-sectional study found that in APOE ε4 carriers, but not APOE ε4 non-carriers, low serum HDL-c levels were positively associated with cognitive impairment and that those with higher HDL levels had higher MMSE scores." (PMID 32231559, 2020). "However, APOE ε4 non-carriers showed normal levels of the majority of these proteins despite the same stage of cognitive impairment and similar levels of neuronal injury markers." (PMID 32460813, 2020). "Whether or not memory and cognitive impairments in humans, carriers of APOEε4 allele, are associated with a disturbed neuronal signaling and the level of NR2A phosphorylation, as in APOE4 expressing mice, is not known." (PMID 30587772, 2018). "In the study, we set out to integrate with new evidence the original RNF219 findings and evaluated whether APOE-ε4 and RNF219/G work in synergy or independently to affect the behavioral or cognitive features of patients affected by mild cognitive impairment (MCI) or AD." (PMID 29755337, 2018). "We think that the classification (using ApoE or PiB) is lower compared to other studies as we aimed to distinguish not MCI due to AD, which is characterized by positive amyloid—PET from HC, but MCI as a heterogeneous entity defined by cognitive impairment from HC (i.e., healthy aging)." (PMID 29081745, 2017). "In addition to that, scientists have proved the increasing accumulation and deposition of Aβ in the absence of ApoE in vivo and in vitro, which were in line with cognitive impairment of this kind of mouse." (PMID 27965573, 2016). "Higher cerebrospinal fluid (CSF) ApoE levels have also been associated with higher cognitive impairment in patients affected by HIV, a finding that was also present in persons with mild cognitive impairment but not in AD patients." (PMID 25071563, 2014). "However, their sample was smaller, older (mean age = 79.2), only females, not taking APOE genotype into account, and included 7 (out of 26) participants with mild cognitive impairment (MCI)." (PMID 22506016, 2012). "Although the involvement of ApoD as a biomarker of brain aging has been described in APOE ε4-related oxidative damage, cognitive impairment, and AD risk, to our knowledge, alcohol effects on ApoD have not been studied in abstinent AUD patients with cognitive impairment." (PMID 38535924, 2024). "Although a link between cognition and APOE ε4 exists in patients with PD, our results suggest that APOE ε4 plays a secondary role when considering multiple factors such as depression, physical activity, and other nonmotor symptoms, which have a stronger impact on cognitive impairment." (PMID 38026513, 2023). "Although this distribution of APOE Ɛ4 homozygotes by clinical status may not represent the general population, the correlation of APOE genotype with ApoE glycosylation was observed before the onset of cognitive impairment." (PMID 37221560, 2023). "In comparison to patients with risk tau haplotypes and risk APOE variants, each one of the patients in GR1 (MAPT + TARDBP + TREM2 cases) had an earlier disease onset (without differences in disease duration), increased cognitive deficits, and a more minor presence of chronic symptoms." (PMID 36474176, 2022). "Moreover, APOE genotypes or haplotypes may not significantly play a role in the COVID-19 cognitive impairment." (PMID 36046159, 2022). "APOE genotypes or haplotypes may not significantly play a role in COVID-19 cognitive impairment." (PMID 36046159, 2022).
Cognitive impairment (continued). "In the model including all participants and a variable indicating the joint classification of lifestyle profile and APOE ε4 genotype, we could observe the same dose–response relationship between lifestyle groups and cognitive impairment among both APOE ε4 carriers and noncarriers." (PMID 34061824, 2021). "The recent characterization of the bEKO mouse model by Lane-Donovan and colleagues, which fortuitously lacks APOE in the brain but shows normal levels in the plasma, suggests that this may be the case, as these animals do not show any cognitive deficits as compared with APOEnull mice." (PMID 30760557, 2019). "Furthermore, potential AD-like mechanisms such as tau pathology, which might contribute to cognitive deficits in ApoE-KO mice, has not been ruled out." (PMID 27965573, 2016). "Genetic characteristics such as the apolipoprotein E (APOE) gene polymorphism, particularly the presence of an ε4 allele (or APOE4 isoform), are frequently linked, not only to hyperlipoproteinemia, but also to AD and cognitive impairment in non-demented adults." (PMID 23874743, 2013). "This study explores the interaction between APOE ε4 (APOE4) and cognitive impairment on non-oscillatory EEG activity." (PMID 41583006, 2025). "Finally, our exploratory analyses provided preliminary evidence that the relationship between high hs-CRP and cognitive impairment was driven by APOE-ε4 non-carriers only, which could indicate that non-carriers may be more susceptible to the detrimental effects of inflammation on cognitive function." (PMID 39807297, 2025). "In addition to the two APOE SNPs, there are >83,500 other SNPs that were used to determine each person's AD PRS (and by extension their genetic risk tertile) and it appears that these are not clearly associated with the cognitive impairment outcome used in this study." (PMID 37139261, 2023). "Differences in quantitative susceptibility mapping (QSM) values between and within groups, including AD patients, individuals with mild cognitive impairment (MCI), and healthy controls (HCs), both APOE-ε4 carriers and non-carriers, were analyzed." (PMID 37284016, 2023). "The relationship between APOE isoforms and Fronto-temporal dementias (FTD), another tauopathy characterized by tau in the absence of Aβ but showing high degree of cognitive impairment, is more obscure." (PMID 35440098, 2022). "In summary, these data support that there are apoE isoform-dependent effects on hAPP/Aβ-induced behavioral alterations and cognitive impairments and Aβ pathology in mouse models containing only human APP and apoE and not the murine counterparts." (PMID 35299942, 2022). "In the current study, we discovered that repeated sevoflurane anesthesia increased hippocampal levels of total ApoE, full‐length ApoE, ApoE fragments, Tau phosphorylation (AT8 and PHF1), as well as cognitive impairment in young mice, but not in adult animals." (PMID 35810473, 2022). "Sevoflurane anesthesia enhanced ApoE mRNA, total ApoE, full‐length ApoE, ApoE fragments, Tau phosphorylation (AT8 and PHF1), and cognitive impairment in young mice, but not in adult mice." (PMID 35810473, 2022). "In this experiment, 58 subjects without cognitive impairment were selected from ADNI-2, and were divided into two groups, APOE e4 carriers and non-carriers, according to their APOE genotype." (PMID 32733231, 2020). "Our finding of an APOE-dependent effect on WMH load suggests a more prevalent and functionally relevant contribution of WMHs to cognitive impairment in AD among APOE ε4 non-carriers." (PMID 25984242, 2015). "After adjustment for age, gender, education, and APOE genotypes (APOE3 and APOE4), the results also showed the same: A significant negative correlation between serotonin levels and cognitive impairment, as indicated by the CDR-SB (r = −0.230, FDR-adjusted p = 0.024)." (PMID 39696587, 2024).
Cognitive impairment (continued). "APOE-ε4 carriers had a higher frequency of cognitive impairment (CDR score ≥ 0.5), higher scores of Braak staging for NFT and CERAD score for NP, and a higher frequency of CAA than APOE-ε4 non-carriers." (PMID 38115150, 2023). "TREM2 mRNA in the dlPFC and PCC was higher in individuals with a clinical diagnosis of AD compared to those with no cognitive impairment (NCI) (p = 0.030, and p = 0.043, respectively) but no different across APOE-ε4 carrier status (p = 0.095 and p = 0.071, respectively)." (PMID 36966244, 2023). "It is necessary to expand the sample size and consciously collect patients with higher CSVD scores for further analysis; third, APOE genotypes were not tested in these patients, which yielded confounding bias due to its correlation with both CSVD markers and cognitive impairment." (PMID 35875803, 2022). "In APOE ε4 non-carriers, most of these protein levels were similar to controls, except for inflammation markers SPP1, FABP3 (also in the replication cohort), and GFAP that were higher in more severe stages of cognitive impairment." (PMID 32460813, 2020). "In addition, neuroimaging studies have showed shrinkage in hippocampal volume in APOE ε4 carriers with mild cognitive impairment (MCI) and AD compared to APOE ε4 non-carriers, which correlated with reduced cognition memory performance." (PMID 30983990, 2019). "Additionally, while our study controlled for age and APOE ε4 status, other potential confounding factors such as hypertension, diabetes, and small vessel disease were not accounted for, which may influence CMH occurrence and cognitive impairment." (PMID 40355774, 2025). "Furthermore, the association of APOE ε2 with markers of hypertensive arteriopathy may not be direct, but rather due to the fact that APOE ε2 carriers tend to have a lower amyloid burden and thus require a greater severity of hypertensive SVD for cognitive impairment to develop." (PMID 35912087, 2022).
diabetes (733 papers, 2002 to 2026). "Among the genetic factors, the influence of Apolipoprotein E (APOE) polymorphisms on DN development has been extensively studied in both type 1 diabetes mellitus (T1DM) and type 2 diabetes mellitus (T2DM) populations." (PMID 39417844, 2025). "Apolipoprotein E (ApoE) affects lipid metabolism and was associated with type 2 diabetes mellitus (T2DM) complications, including diabetic peripheral neuropathy (DPN)." (PMID 41488146, 2025). "AD and COVID-19 have common risk factors including age hypertension diabetes cardiovascular disease and the presence of the apolipoprotein E ε 4 allele." (PMID 40356629, 2025). "A cross‐sectional study found that the impact of diabetes on cognitive performance was more pronounced in individuals carrying one or more APOE ε4 alleles." (PMID 40296350, 2025). "APOE was associated with sex and race in AD, with diabetes in PD, with resting heart rate and chronic obstructive pulmonary disease (COPD) in PDD, and with age, body mass index, and hypertension in nonimpaired controls." (PMID 40665049, 2025). "The associations of PSD with atrial fibrillation, prediabetes/diabetes, and MetS were also strengthened, while the associations with prior stroke and APOE-ε4 homozygosity were attenuated." (PMID 40893447, 2025). "Risk factors for AD include cardiovascular diseases, age, high cholesterol, diabetes, positive family history, traumatic brain injury, and the presence of variant 4 of apolipoprotein E (APOE4), amongst other factors yet to be described." (PMID 39199508, 2024). "In this study, we found treatment of MSC-Exos in STZ treated ApoE KO mice constrained diabetes pathologies of hyperglycemia and body weight loss." (PMID 38390337, 2024). "It means that hypertensive patients who are obesity, have history of smoking and diabetes mellitus, and carried the APOE ɛ3/ɛ4 genotype need to be aware of the risk of developing coronary atherosclerosis." (PMID 39261765, 2024). "Vitamin D deficiency, insulin resistance, dyslipidemia, and APOE genotyping are implicated in the pathogenesis of obesity and type 2 diabetes mellitus (T2DM)." (PMID 39138505, 2024). "Apolipoprotein E gene polymorphism is associated with cardiovascular disease in patients with diabetes by affecting the lipid profile." (PMID 38929578, 2024). "Participants who developed PD were more likely to be older, male, with higher blood pressure, have a history of diabetes, hyperlipidemia and stroke, take psychotropic medications, and be APOE and GBA variants carriers." (PMID 38982064, 2024). "Other studies have found that APOE ɛ4 allele was associated with an increased risk of diabetes mellitus complicated with CAD." (PMID 39261765, 2024). "In summary, overweight (BMI ≥ 24.0 kg/m2), advanced age, history of smoking, diabetes mellitus, and APOE ɛ3/ɛ4 genotype were independent risk factors for coronary atherosclerosis in patients with hypertension." (PMID 39261765, 2024). "Overweight (BMI ≥ 24.0 kg/m2), advanced age, history of smoking, diabetes mellitus, and APOE ɛ3/ɛ4 genotype were independent risk factors for coronary atherosclerosis in hypertensive patients." (PMID 39261765, 2024). "The CNS effects of insulin resistance and diabetes were shown to be more marked in individuals with the apolipoprotein E alleles ε4 and ApoE-ε4 allele, which was found to be present in 16.6% of patients with NALFD." (PMID 38542310, 2024). "These include a family history of the disease, education level, a diet high in fat content, high blood pressure, diabetes, a history of head injuries, and specific genetic predispositions like the presence of the APOE ε4 (Apolipoprotein E ε4) gene variant." (PMID 38473858, 2024). "Apolipoprotein E (APOE) is widely recognized as a significant gene implicated in the pathophysiology of cardiovascular diseases, neuropsychiatric diseases, diabetes, and nephropathies." (PMID 38540308, 2024).